TGFB2 (transforming growth factor beta 2)
Diseases named in the same sentence as TGFB2 in open-access papers (continued):
Sharing a sentence is not in itself a finding about the gene and the disease.
diabetic neuropathy (2 papers, 2025). A chronic, pathological complication associated with diabetes mellitus, where nerve damages are incurred due to diabetic microvascular injury involving small blood vessels that supply these nerves, resulting in peripheral and/or autonomic nerve dysfunction. "The upregulation of TRPV4/Piezo1 transcription by TGFβ2 predicts exaggerated responsiveness to mechanical loading, as reported for chemotherapy, neuropathic pain, cancer, and diabetic neuropathy." (PMID 39574569, 2025). "The upregulation of TRPV4/PIEZO1 transcription by TGFβ2 predicts exaggerated responsiveness of the outflow pathway to mechanical loading, as reported for TRPV4-dependent mechanical hyperalgesia in chemotherapy, neuropathic pain, cancer, and diabetic neuropathy." (PMID 40552711, 2025).
diffuse intrinsic pontine glioma (2 papers, 2023 to 2024). A neuroglial tumor that arises from the middle portion of the brain stem. "Additionally, TGFB2 (Transforming Growth Factor Beta 2) has been identified as a predictor of poor treatment outcomes in pediatric diffuse intrinsic pontine glioma." (PMID 38474320, 2024).
endometrial tumor (2 papers, 2010 to 2022). "The fact that TGFB2 shares 2 β8 cysteines and an endometrial adenoma phenotype with INHA and INHBB implies that TGFB2 can heterodimerize with either to prevent endometrial tumor formation." (PMID 36214621, 2022).
gingival overgrowth (2 papers, 2009 to 2021). Excessive growth of the gingiva either by an increase in the size of the constituent cells (gingival hypertrophy) or by an increase in their number (gingival hyperplasia). "The TGFB2 gene was recently identified as a key factor in drug-induced gingival overgrowth and autocrine TGFβ2 signaling could contribute to the pathogenesis of hereditary or pharmacological-induced gingival fibromatosis." (PMID 34777248, 2021).
Glucose intolerance (2 papers, 2021 to 2022). Glucose intolerance (GI) can be defined as dysglycemia that comprises both prediabetes and diabetes. "In vivo zebrafish and mouse models exhibited glucose intolerance, decreased peak GSIS, decreased expression of β-cell identity markers, increased insulin and glucagon co-staining cells, and reduced Tgfb2 and Smad2 expression." (PMID 34246804, 2021).
Hearing impairment (2 papers, 2021 to 2025). A decreased magnitude of the sensory perception of sound. "The protein–protein interaction network analysis identified prominent interaction characteristics among neighboring genes of tinnitus-associated loci (RUNX2, TGFB2, CDH1, and DEFB family) and hearing-loss-associated loci (CDH1, PRR19, and MAGOHB)." (PMID 40362371, 2025). "Finally, the PPI networks identified in this study, particularly those involving RUNX2, TGFB2, and CDH1, may serve as the foundation for novel therapeutic approaches aimed at restoring auditory function in patients who have already experienced radiotherapy-induced hearing impairment." (PMID 40362371, 2025).
infarction (2 papers, 2019 to 2020). A localised pathological necrosis of tissue resulting from obstruction of the blood supply usually by a thrombus, an embolus, or vascular torsion. "As determined by Western blot and ELISA, relatively high expression of TGFβ1 and TGFβ2 was detected in the early phase of MI, while TGFβ1 and TGFβ2 expressions decreased with the infarction time." (PMID 30983140, 2019).
ischemic cardiomyopathy (2 papers, 2025). Ischemic cardiomyopathy is a cardiomyopathy in which a weakness in the muscle of the heart due to inadequate oxygen delivery to the myocardium with coronary artery disease being the most common cause. "While both cell types are known to produce TGF‐beta, our findings further support the role of fibroblast‐derived TGFB2 in promoting fibrosis, inflammation and impaired tissue repair, contributing to the progression of ischemic cardiomyopathy." (PMID 40344498, 2025).
kidney inflammation (2 papers, 2012 to 2022). "Previous reports have shown a transient upregulation of TGFb2 in acute-phase experimental nephritis, and this change in expression correlated with fibrosis progression." (PMID 22235299, 2012).
lymphoma (2 papers, 2017 to 2021). A malignant (clonal) proliferation of B- lymphocytes or T- lymphocytes which involves the lymph nodes, bone marrow and/or extranodal sites. "This identified upregulation of TGFβ signalling as the most affected molecular pathway in Eμ-Myc;shBcor lymphomas (Bonferroni corrected P=0.0058), with enhanced expression of TGFβ pathway members (Cited1, Bambi, Acvr2b, Smad3, Mapk12, Tgfb2)." (PMID 28262675, 2017). "TCLlnc1/HNRNPD/YBX1 complex upregulated transcription of TGFB2 and TGFBR1 genes, activated the tumor growth factor-β signaling pathway, resulting in lymphoma progression, and might be a potential target in PTCL." (PMID 33767152, 2021).
macular holes (2 papers, 2020 to 2025). A hole in the macula of the retina. "In recent years, a second operation with transforming growth factor beta 2 application or autologous platelet concentrate inserted inside the macular hole was proposed to obtain the closure of FTMH." (PMID 33029387, 2020).
mastitis (2 papers, 2022 to 2025). Inflammation of breast tissue during lactation or postpartum due to an obstructed duct or infection. "It should be highlighted that mastitis did not modify the levels of TGFβ2, the most abundant cytokine in milk." (PMID 35079053, 2022). "The stability of TGFβ2 levels in mastitis milk samples, would support, at least partially, that mastitis does not constitute a problem for the lactating infant." (PMID 35079053, 2022).
sarcoidosis (2 papers, 2023 to 2024). Sarcoidosis is a multisystemic disorder of unknown cause characterized by the formation of immune granulomas in involved organs. "The other variant, i.e., the intronic rs1891467 in the TGFB2 gene, has been associated with sarcoidosis." (PMID 38232165, 2024). "Two of the SNPs in this genetic signature, namely rs1891467 near TGFB2 and rs7667298 near KDR, had been reported to be associated with an acute course of sarcoidosis before in a German cohort." (PMID 37621457, 2023). "TGFB2 and KDR variants were reported to be associated in a German cohort with an acute course of sarcoidosis and variants of TNFRSF1B are known to influence the response to anti-TNF therapy in sarcoidosis." (PMID 37621457, 2023).
acute GVHD (1 paper, 2022). "A predictive model using five of such polymorphisms (CXCL12 rs2839695, IL12A rs7615589, KIR3DL1 rs4554639, TGFB2 rs5781034 for the recipient and CD48 rs2295615 for the donor) together with the development of acute GVHD grade III/IV improved risk stratification of CMV reactivation." (PMID 35525883, 2022).
adenoma (1 paper, 2019). A neoplasm arising from the epithelium. "All investigated and expressed target genes, CDKN1B, PTPN13, RND3, SOX2 and ZEB2, were down-regulated in adenoma compared to normal mucosa of CRC N0, except ONECUT2 and TGFB2, which were up-regulated." (PMID 31623346, 2019). "In contrast to adenoma, investigated target genes CDKN1B, PTPN13, RND3, SOX2 and ZEB2 were up-regulated in CRC N0, except ONECUT2 and TGFB2, which were down-regulated." (PMID 31623346, 2019). "Moreover, PTPN13, SOX2 and ZEB2 showed detectable expression only in two out of 10 adenoma cases, whereas ONECUT2 and TGFB2 were up-regulated." (PMID 31623346, 2019).
Alzheimer disease (1 paper, 2023). A progressive, neurodegenerative disease characterized by loss of function and death of nerve cells in several areas of the brain leading to loss of cognitive function such as memory and language. "In turn, the increased TGFB2 binds to the extracellular domain of amyloid beta precursor protein and triggers a neuronal cell death pathway in Alzheimer’s disease." (PMID 37107654, 2023). "Regarding TGFB2, while its expression is increased in the postmortem brains of patients with SCZ and psychotic BD, due to its promoter DNA hypomethylation, other studies have shown that TGFB2 is over-expressed in the neurons of patients with Alzheimer’s disease." (PMID 37107654, 2023).
B-cell lymphoma (1 paper, 2014). "In addition, further biological studies are needed to determine if TGFβ2 and TNFAIP3 are therapeutic targets for B-cell lymphoma." (PMID 25364581, 2014). "Additionally, in the different B-lymphocyte malignant cell lines, the expression levels of BMPR2, EP300, TGFβ2, and TNFAIP3 mRNA were quite different, which may be related to the heterogeneity of B-cell lymphoma." (PMID 25364581, 2014).
Bethlem myopathies (1 paper, 2024). "A recent study also found many of these same variants in EDS patients, several previously associated with other diseases (e.g., in the TGFB2/3 genes associated with Loeys–Dietz syndromes (M614816+) and the COL6/12 genes associated with Bethlem myopathies (M158810+))." (PMID 38534782, 2024).
bone tumors (1 paper, 2012). "High-level amplification of TGFβ2 (1q41), CCND3 (6p21), WI-6509 (11qtel), SHGC-5557 (12ptel), TCL1A (14q32.1), CREBBP (16q13.3), HIC1 (17p13.3), THRA (17q11.2), AFM217YD10 (17qtel), LAMA3 (18q11.2), RUNX1 (21q22.3) and D22S543 (22q11), was commonly observed in aggressive bone tumors." (PMID 23199169, 2012).
brainstem tumors (1 paper, 2024). "Our study characterizes the prognostic impacts of TGFB2 and IFNGR2 in brainstem tumors, which provide potential insights into the prognostic role of these molecules in pbDMG patients." (PMID 38255296, 2024).
Cachexia (1 paper, 2023). Severe weight loss, wasting of muscle, loss of appetite, and general debility related to a chronic disease. "Overexpression and administration of TGFβ2 has been shown to induce cachexia in mice, rats, and humans." (PMID 37701438, 2023).
Cerebral cavernous malformation 2 (1 paper, 2010). "Cerebral cavernous malformation 2 (CCM2), insulin-like growth factor binding protein 3 (IGFBP3), sarcospan (Kras oncogene-associated gene); (SSPN), and transforming growth factor, beta 2 (TGFB2) were selected and screened as candidates under these criteria." (PMID 21179236, 2010).
cerebral malaria (1 paper, 2010). A sequestration of Plasmodium falciparum in the brain, which can cause coma and/or seizures. "Association results for cerebral malaria risk single-nucleotide polymorphisms (SNPs) genotyped in TGFB2, CD36, HBB and HMOX1 genes." (PMID 20585394, 2010).
childhood asthma (1 paper, 2012). "Although we did not investigate the reason for the higher levels of TGF-β2 expression by PBECs from asthmatic donors, it has been reported that there are polymorphisms in the TGFB2 gene promoter that are associated with childhood asthma." (PMID 22970254, 2012).
chorioamnionitis (1 paper, 2024). A morphologic finding indicating inflammation of the fetal sac membranes. "Membranes with chorioamnionitis display increased miR-223 and miR-338 expression, and miR-223 target genes (SPINK5, TGFB2, and IFNB1) are involved in the biological processes of negative regulation of immune and anti-inflammatory responses." (PMID 39574982, 2024).
chronic hepatitis B (1 paper, 2021). "TGFβ2 has suppressive effects on IL-2-dependent T-cell growth and is significantly down-regulated in chronic hepatitis B patients." (PMID 34440714, 2021).
chronic obstructive pulmonary disease (1 paper, 2024). A chronic and progressive lung disorder characterized by the loss of elasticity of the bronchial tree and the air sacs, destruction of the air sacs wall, thickening of the bronchial wall, and mucous accumulation in the bronchial tree. "Our example applications highlight the potential significance of BSG receptor in SARS-CoV-2 infection as well as the involvement of HHIP and TGFB2 in the development and progression of chronic obstructive pulmonary disease." (PMID 38617561, 2024).
cleft lip (1 paper, 2021). Congenital defect in the upper lip where the maxillary prominence fails to merge with the merged medial nasal prominences. "MalaCards showed that TGFB2 is related to cleft lip/palate and oral cleft." (PMID 33732700, 2021).
cleidocranial dysplasia (1 paper, 2023). "Osteoblast-specific overexpression of Tgfb2 using Ocn promoter caused a mineralization defect and severe hypoplasia of clavicles similar to cleidocranial dysplasia." (PMID 37445982, 2023).
congenital adrenal hyperplasia (1 paper, 2018). Congenital adrenal hyperplasia (CAH) is an inherited endocrine disorder caused by a steroidogenic enzyme deficiency that is characterized by adrenal insufficiency and variable degrees of hyper or hypo androgyny manifestations, depending of the type and the severity of the disease. "Abnormal up‐regulation of TGFβ2/3 expression in patients with TNX‐related Ehlers‐Danlos syndrome phenotypes plus congenital adrenal hyperplasia was reported." (PMID 29160014, 2018).
congenital contractural arachnodactyly (1 paper, 2024). Congenital contractural arachnodactyly (CCA, Beals syndrome) is a connective tissue disorder characterized by multiple flexion contractures, arachnodactyly, severe kyphoscoliosis, abnormal pinnae and muscular hypoplasia. "Genetic variants in genes including TGFBR1, TGFBR2, TGFB2, TGFB3, SMAD2, and SMAD3 result in Loeys–Dietz syndrome and are reported to cause Marfan-like phenotypes and variants in FBN2 and COL3A1 result in congenital contractural arachnodactyly and Ehlers–Danlos syndrome type IV." (PMID 38791509, 2024).
congenital heart disease (1 paper, 2023). A heart disease that is present at birth. "Loss of TGFβ2 in mice causes cardiac cushion remodeling defects resulting in congenital heart disease." (PMID 38132651, 2023). "Thus, the TGFβ2 and Hippo pathway integration represents an important step in understanding the etiology of congenital heart disease." (PMID 38132651, 2023).
degenerative myopia (1 paper, 2025). "Specifically, it recognized two genes within the TGF-Beta signaling pathway—TGFB3 (ENSP00000238682) and TGFB2 (ENSP00000355896)—as being associated with degenerative myopia, a connection not made by the RWR method." (PMID 40110040, 2025).
dementia (1 paper, 2020). Loss of intellectual abilities interfering with an individual's social and occupational functions. "Interestingly, the levels of TGFβ-2 were previously found to be increased in the neocortex of AD and dementia with Lewy bodies and were positively correlated with neuropathological markers of disease severity." (PMID 32493431, 2020).
disc degeneration (1 paper, 2025). "Bone morphogenesis-related genes (TGFB2, BMP4, and THBS1) were enriched in NPPCs, suggesting that NPPCs undergo osteogenic differentiation during the progression of disc degeneration in C2." (PMID 40883814, 2025).
endometrial adenocarcinoma (1 paper, 2022). "A second β8 region mutation TGFB2 β8Cys@3 (Cys256Stop) is found in endometrial adenocarcinomas." (PMID 36214621, 2022). "Cysteine mutations in TGFB2, INHA, and INHBB associated with endometrial adenocarcinoma plus cysteine mutations in TGFB2 and TGFB3 with Loeys–Dietz syndrome lead to the hypothesis that TGFB2 is capable of heterodimerization with numerous partners." (PMID 36214621, 2022). "TGFB2 β8Cys@3 has Cys256Stop identified in endometrial adenocarcinomas." (PMID 36214621, 2022).
Ewing sarcoma (1 paper, 2025). A small round cell tumor that lacks morphologic, immunohistochemical, and electron microscopic evidence of neuroectodermal differentiation. "We also determined the expression of other TGFβ isoforms, TGFB2 and TGFB3, in the immune compartment of Ewing sarcomas and found that TGFB1 is the predominant isoform expressed." (PMID 40858520, 2025).
Insulin resistance (1 paper, 2020). Increased resistance towards insulin, that is, diminished effectiveness of insulin in reducing blood glucose levels. "Insulin resistance-associated factors, such as IGF1 and IGFALS, and inflammation-related factors, such as CSF1 and TGFβ2, were all highly enriched in the MetS group." (PMID 32133283, 2020).
Intellectual disability (1 paper, 2021). "According to the DECIPHER database, a patient with deletion in the region of the TGFB2 gene showed congenital diseases, including CP, coarse facial features, intellectual disability, and ventricular septal defect." (PMID 33732700, 2021).
Intervertebral Disc Degeneration (1 paper, 2024). "The predictive analysis identifies the TGFβ-1 gene as the most promising candidate associated with Intervertebral Disc Degeneration (IDD), with isoforms TGFβ-2 and TGFβ-3 also receiving prioritization." (PMID 38745993, 2024).
intrauterine growth restriction (1 paper, 2026). "In a broader view, supplement with TGFβ2 might also be used for treatment against other placenta‐originated adverse pregnancy outcomes, such as eclampsia, intrauterine growth restriction, or premature birth." (PMID 41168951, 2026).
kidney cancer (1 paper, 2014). Primary or metastatic malignant neoplasm involving the kidney. "We used quantitative RT‐PCR to measure the levels of three TGF‐beta pathway components (TGFB2, INHBA, and SMAD3) and two TGF‐beta targets (THBS1 and CDKN2B) which were previously found to be significantly lower in FLCN‐deficient kidney cancer cells and tumors." (PMID 25121506, 2014).
Kyphoscoliosis (1 paper, 2023). An abnormal curvature of the spine in both a coronal (lateral) and sagittal (back-to-front) plane. "Tgfβ2−/− mice exhibit multiple axial and appendicular skeletal patterning defects including kyphoscoliosis, fused vertebral column, abnormal curvature of the ribs, fused ribs, bifid ribs, and bifurcation of the sternum in mice." (PMID 36910145, 2023).
left ventricular hypertrophy (1 paper, 2016). Enlargement of the LEFT VENTRICLE of the heart. "In a rat model of left ventricular hypertrophy all three TGFβ isoforms were induced upon cardiac remodeling, however TGFB2 expression level increased earlier and was more robust than the other two isoforms." (PMID 26918958, 2016).
liver inflammation (1 paper, 2021). "Additionally, a recent study has also reported that the administration of DSS changed the expression of pro-and anti-inflammatory cytokines such as IL-1β, IL-10, and TGFb-2, suggesting that intestinal inflammation led to liver inflammation, thus, these results supported our finding again." (PMID 34603071, 2021).
lupus (1 paper, 2021). "Our analysis of sCTLA-4 in the lupus patient cohort indicates that increased sCTLA-4 production is not, however, exclusively dependent on TGFβ2 but may be associated particularly with cancers known to secrete high levels of the TGFβ2 isoform." (PMID 35069536, 2021).
mammary adenocarcinoma (1 paper, 2004). "Nevertheless, the expression of MUC4 is also regulated by TGFβ2, post-translationally and post-transcriptionally in normal and mammary adenocarcinoma cells, respectively." (PMID 14760381, 2004).
microphthalmia (1 paper, 2021). Congenital or developmental anomaly in which the eyeballs are abnormally small. "Of the seven patients diagnosed with colobomatous microphthalmia, potentially disease-causing variants were identified in three index patients (43%) in three different genes (PUF60, BRPF1, and TGFB2)." (PMID 33418956, 2021).
myeloid leukemia (1 paper, 2014). A clonal proliferation of myeloid cells and their precursors in the bone marrow, peripheral blood, and spleen. "In this study, quantitative reverse transcription polymerase chain reaction (qRT-PCR) was used to analyze the expression levels of BMPR2, EP300, TGFβ2, and TNFAIPI3 in B-lymphoma and myeloid leukemia cell lines." (PMID 25364581, 2014). "Although BMPR2, EP300, TGFβ2, and TNFAIPI3 have been studied in lymphoma or leukemia, no report has compared the expression of the four genes among B-lymphoma cells, the healthy control, and myeloid leukemia." (PMID 25364581, 2014).
nicotine addiction (1 paper, 2018). "In addition, several other COPD GWAS loci have strong candidate genes, such as the nicotinic acetylcholine receptor genes that have been related to nicotine addiction (CHRNA3 and CHRNA5) and TGFB2 (part of the TGFBeta pathway)." (PMID 30262855, 2018).